GABARAPL1 (GABA type A receptor associated protein like 1)
Diseases named in the same sentence as GABARAPL1 in open-access papers (continued):
Sharing a sentence is not in itself a finding about the gene and the disease.
glioma (3 papers, 2022 to 2025). A benign or malignant brain and spinal cord tumor that arises from glial cells (astrocytes, oligodendrocytes, ependymal cells). "Exposure to oxidative stress, such as treatment with hydrogen peroxide (H2O2), upregulates GABARAPL1 mRNA, and protein levels in rat C6 glioma cells." (PMID 41333685, 2025). "For the glioma TCGA cohort, the risk score was calculated as follows: risk score = (0.6457 × PGAM5 expression) + (0.8062 × SQSTM1 expression) + (−0.4834 × ATG9A expression) + (−0.6285 × GABARAPL1 expression)." (PMID 36292980, 2022). "The results implied that advanced age, high-grade tumor, 1p/19q non-codeletion, IDH-non mutation, low expression of ATP6V1G2, GABARAPL1 and GOT1 might be poor prognostic factors for glioma patients." (PMID 35896732, 2022). "Also, K–M curves in 313 gliomas sample through CGGA database showed that low expression of ATP6V1G2, GABARAPL1 and GOT1 was associated with poor prognosis, which was consistent with the results from the TCGA database." (PMID 35896732, 2022). "Overall, the expression of ATP6V1G2, GABARAPL1 and GOT1 was significantly elevated in low-grade glioma compared to high-grade glioma." (PMID 35896732, 2022). "The expression of ATP6V1G2, GABARAPL1, GOT1 along with common glioma characteristics (age, gender, race, tumor grade, 1p/19q status, IDH status) were included in the univariate Cox regression analysis." (PMID 35896732, 2022). "Combined with their high expression in non-glioma samples, we speculated that ATP6V1G2, GABARAPL1, and GOT1 might be suppressor genes for glioma." (PMID 35896732, 2022).
lung carcinoma (3 papers, 2021 to 2023). "Conversely, CHIL31 depletion decreased the conversion from LC3-I to LC3-II in lung cancer cell lines as well as the expression of GABARAPL1, ATG5, p62, and Beclin-1." (PMID 37340009, 2023). "Here, we found that GABARAPL1—an autophagy-related gene—was increased in human NSCLC mesenchymal tumors compared to epithelial tumors, and induction of EMT in an A549 lung cancer cell line by TGF-β/TNF-α cytokines also led to an increase in GABARAPL1 expression." (PMID 34681055, 2021).
Parkinson disease (3 papers, 2013 to 2025). A progressive degenerative disorder of the central nervous system characterized by loss of dopamine producing neurons in the substantia nigra and the presence of Lewy bodies in the substantia nigra and locus coeruleus. "Moreover, GABARAPL1 can interact with α-synuclein, a protein shown to form protein aggregates and deleterious lewy bodies in Parkinson's disease, and displays a higher binding affinity for α-synuclein oligomers compared to monomers." (PMID 23690988, 2013). "Finally, GABARAPL1 expression was particularly intense in motoneurons in the embryo and in neurons involved in somatomotor and neuroendocrine functions in the adult, particularly in the substantia nigra pars compacta, a region affected in Parkinson's disease." (PMID 23690988, 2013). "According to the GSEA results, the ACBD5, GABARAPL1, and HSPA8 were involved in five pathways, including proteasome, oxidative phosphorylation, citrate cycle TCA cycle, Parkinsons disease, and aminoacyl tRNA biosynthesis." (PMID 40002775, 2025).
schizophrenia (3 papers, 2016 to 2024). A major psychotic disorder characterized by abnormalities in the perception or expression of reality. "When we compared the full set of female and male schizophrenia DEGs across brain regions, we found an additional three overlapping genes (CD99, GABARAPL1, and LIN7B) shared with the caudate nucleus." (PMID 38730231, 2024).
acute myeloid leukemia (2 papers, 2020 to 2022). Acute myeloid leukemia (AML) is a group of neoplasms arising from precursor cells committed to the myeloid cell-line differentiation. "The risk score for the acute myeloid leukemia TCGA cohort was calculated as follows: risk score = (0.4655 × SQSTM1 expression) + (−0.2004 × GABARAPL1 expression)." (PMID 36292980, 2022).
Alzheimer disease (2 papers, 2023). A progressive, neurodegenerative disease characterized by loss of function and death of nerve cells in several areas of the brain leading to loss of cognitive function such as memory and language. "The aim of this study was to further investigate the role of genes identified in our previous studies as relevant for the pathophysiology of Alzheimer’s disease and T2DM comorbidity, namely ATG16L1, ATG16L2, GABARAP, GABARAPL1, GABARAPL2, and SQSTM1." (PMID 36901549, 2023).
breast tumors (2 papers, 2010 to 2020). "GABARAPL1 expression is robustly downregulated in breast tumors and those patients with high GABARAPL1 levels have a low risk of metastasis." (PMID 32801338, 2020). "Gabarapl1 expression has been analysed in this study for the first time in a retrospective cohort of 265 breast tumours." (PMID 20197771, 2010).
depression (2 papers, 2009 to 2013). "GABARAPL1 expression in GABAergic neurons becomes particularly interesting for studies of depression." (PMID 23690988, 2013). "For instance, in the hippocampus, all differentially expressed GABAergic genes were clearly up-regulated in suicides with major depression (GABARAPL1, GABARA4 and GABARB1) and with low expression among suicides without history of depressive disorders, suggesting a depression specific effect." (PMID 19668376, 2009).
head and neck squamous cell carcinoma (2 papers, 2017 to 2021). A squamous cell carcinoma that arises from any of the following anatomic sites: lip and oral cavity, nasal cavity, paranasal sinuses, pharynx, larynx, and salivary glands. "In head and neck squamous cell carcinoma, the high expression level of GABARAPL1 is associated with the poor prognosis of patients." (PMID 34759953, 2021). "In head and neck squamous cell carcinoma, high expression level of GABARAPL1 is associated with poor outcome of patients." (PMID 29088804, 2017). "In head and neck squamous cell carcinoma high expression level of GABARAPL1 was associated with poor outcome of patients." (PMID 29088804, 2017).
kidney adenocarcinoma (2 papers, 2021 to 2023). "To determine the role of GABARAPL1 during EMT, we used the CRISPR/Cas9 technology in A549 and ACHN kidney adenocarcinoma cell lines to deplete GABARAPL1." (PMID 34681055, 2021).
liver cancer (2 papers, 2023). An epithelial or non-epithelial malignant neoplasm that arises from the liver. "In liver cancer, loss of GABARAPL1 gives ferroptosis resistance to cancer stem-like cells." (PMID 37790613, 2023). "SMAD2 and SMAD3 correlated with autophagy-related scores (based on ATG12, ATG7, ATG3, ATG5, ATG4B, PIK3C3, PRKAA2, and GABARAPL1) in liver cancer." (PMID 37790613, 2023).
nasopharyngeal carcinoma (2 papers, 2024 to 2025). A carcinoma arising from the nasopharyngeal epithelium. "In addition to TNBC, GABARAPL1 overexpression in nasopharyngeal carcinoma (NPC) can induce autophagosome formation, reduce HIF-2α, and then promote apoptosis of nasopharyngeal carcinoma cells to inhibit tumor cell growth." (PMID 40900801, 2025).
Obesity (2 papers, 2012 to 2021). Accumulation of substantial excess body fat. "Therefore, similar to our in vitro analysis, we evaluated FoxO induced autophagy markers Gabarapl1 and Beclin-1 in the obesity-induced mouse OA model treated with or without liposomal injections of adenosine or CGS21680." (PMID 33441836, 2021).
triple-negative breast carcinoma (2 papers, 2017 to 2019). An invasive breast carcinoma which is negative for expression of estrogen receptor (ER), progesterone receptor (PR), and human epidermal growth factor receptor 2 (HER2). "The purpose of this study was to investigate the expression, prognostic roles and functions of GABARAPL1 in triple negative breast cancer (TNBC)." (PMID 29088804, 2017). "However, the role of GABARAPL1 is controversial with a study showing that downregulation of GABARAPL1 suppresses tumorigenesis and metastasis in triple negative breast cancer cells." (PMID 31803623, 2019). "We then detected the expression level of GABARAPL1 in 20 TNBC tissues and their matched adjacent normal tissues (Normal-1), together with 20 non-triple-negative breast cancer (NTNBC) tissues and their matched adjacent normal tissues (Normal-2)." (PMID 29088804, 2017).
viral infection (2 papers, 2022 to 2023). "To definitively identify the role of GABARAP family members during viral infection, we performed individual silencing of GABARAPL1 or GABARAPL2 in HeLa cells." (PMID 36044516, 2022). "As per viral infection, NIC and virus treated cells (at 48 h) also saw an up-regulation of GABARAPL1, MAP1LC3A, USP30, BMF, and TBK1; WDR81 was also down-regulated in the NIC and virus treatment at 48 h." (PMID 37901834, 2023).
autoimmune thyroid disease (1 paper, 2025). Inflammatory disease of the thyroid gland due to autoimmune responses leading to lymphocytic infiltration of the gland. "The GSEA findings indicate that GABARAPL1 is significantly enriched in immune-related pathways in AD, encompassing pathways such as autoimmune thyroid disease and cytokine-cytokine receptor interaction." (PMID 39919076, 2025).
Cachexia (1 paper, 2017). Severe weight loss, wasting of muscle, loss of appetite, and general debility related to a chronic disease. "We observed that p-AMPK(Thr172) occupies the MAFbx/Atrogin1, MuRF1, and GABARAPL1 promoters and that its association increased during cachexia." (PMID 29167426, 2017). "BRD2 associates with MAFbx/Atrogin1 and GABARAPL1 promoters during cachexia, and this association is abrogated by (+)-JQ1 treatment." (PMID 29167426, 2017). "Because of BRD2 overlapping regulation in several subsets of BRD4 targets, we investigated BRD2 ability to engage MAFbx/Atrogin1, MuRF1, and GABARAPL1 loci, during cachexia." (PMID 29167426, 2017).
cataract (1 paper, 2021). Partial or complete opacity of the crystalline lens of one or both eyes that decreases visual acuity and eventually results in blindness. "Moreover, GABARAPL1 gene expression in patients with AMD was significantly higher than that in patients with cataracts as our control group (p = 0.013)." (PMID 33673354, 2021).
chronic hepatitis B virus infection (1 paper, 2023). Chronic form of hepatitis B infection. "In PBMCs from patients with chronic hepatitis B virus infection, expression of 18 autophagy-modulating genes was downregulated including GABARAPL1, Atg7 and CTSB as well as LC3-II protein levels." (PMID 36994103, 2023).
colorectal cancer (1 paper, 2021). A primary or metastatic malignant neoplasm that affects the colon or rectum. "Real-time PCR array of autophagy-related genes showed that GABARAPL-1 was significantly upregulated in colorectal cancer cells, which was confirmed by western blot and immunofluorescence results." (PMID 35201430, 2021). "Interrupting GABARAPL-1 activity can affect both autophagy and apoptosis in colorectal cancer cells, suggesting crosstalk between the two processes." (PMID 35201430, 2021). "We discovered that sodium selenite treatment induced the crosstalk between autophagy and apoptosis through regulating AMPK/FoxO3a/GABARAPL1 signaling pathway in colorectal cancer cells." (PMID 35201430, 2021). "Collectively, these results show that sodium selenite could induce ROS/AMPK/FoxO3a/GABARAPL-1-mediated autophagy and downregulate apoptosis in both colorectal cancer cells and colon xenograft model." (PMID 35201430, 2021).
diffuse gastric adenocarcinoma (1 paper, 2021). An adenocarcinoma arising from the stomach. "Four DEGs including ATG10, ATG16L2, ULK4 and GABARAPL1 showed differences in diffuse gastric adenocarcinoma subgroup, while other four DEGs including ATG7 (probe 224025_s_at), GABARAPL1, WIPI2 and GABARAPL3 showed differences in gastric intestinal type adenocarcinoma subgroup." (PMID 33604190, 2021).
endometriosis (1 paper, 2016). The growth of functional endometrial tissue in anatomic sites outside the uterine body. "In contrast to the observations in the lesions, we identified increased protein levels of beclin-1, LC3B, LC3A, and GABARAPL1 in uterine horns from endometriosis-induced mice compared with uterine horns from controls, with a concurrent increase in lipid droplets." (PMID 26775710, 2016).
gastric intestinal type adenocarcinoma (1 paper, 2021). An adenocarcinoma of the stomach arising on a background of intestinal metaplasia. "Histological stratification analysis showed that GABARAPL1 was down-regulated in all types of GC compared with normal tissues, with fold change of −2.321 in intestinal gastric adenocarcinoma, −2.287 fold in diffuse adenocarcinoma and −2.622 fold in mixed adenocarcinoma." (PMID 33604190, 2021).
glioblastoma (1 paper, 2021). The most malignant astrocytic tumor (WHO grade IV). "This increase in GABARAPL1 mRNA level upon siRNA-mediated NMD inhibition was also observed in the glioblastoma cells U87." (PMID 34680418, 2021).
HCMV infection (1 paper, 2019). "Two LC3 homologs, GABARAPL1 and GATE16, also accumulated during HCMV infection and were associated with the vAC, in proximity with fragmented Golgi stacks." (PMID 30872707, 2019). "Immunoblot analysis of GABARAPL1 and GATE16 expression confirmed that the proteins accumulated during HCMV infection, whereas their expression is less modified by starvation-induced autophagy." (PMID 30872707, 2019). "Moreover, we described for the first time that LC3 and two GABARAP homologs (GABARAPL1 and GATE16) were present in the vAC, mainly at the outer edge, during HCMV infection." (PMID 30872707, 2019).
hearing loss (1 paper, 2025). "AG-induced hearing loss can be completely or partially prevented by reducing the expression of Ripor2, Gabarap, Lc3β, Pink1, Prkn, or Gabarapl1, as identified in this study." (PMID 39928869, 2025). "Another possibility is that, despite sharing 87% amino acid identity, GABARAP and GABARAPL1 may have slightly different functions in autophagy pathway and AG-induced hearing loss." (PMID 39928869, 2025). "In this study, we identified Gabarapl1 as another gene essential for AG-induced hearing loss." (PMID 39928869, 2025). "This study, using genetic approaches along with morphological and functional assays, reveals that both GABARAPL1 and GABARAP are essential for AG-induced hearing loss, with GABARAP playing a more prominent role." (PMID 39928869, 2025).
Huntington disease (1 paper, 2025). Huntington disease (HD) is a rare neurodegenerative disorder of the central nervous system characterized by unwanted choreatic movements, behavioral and psychiatric disturbances and dementia. "Additionally, the decreased ACBD5 expression level was associated with Huntington’s disease, while high GABARAPL1 and HSPA8 expression levels were concentrated in ECM receptor interaction." (PMID 40002775, 2025).
Insulin resistance (1 paper, 2023). Increased resistance towards insulin, that is, diminished effectiveness of insulin in reducing blood glucose levels. "Significantly elevated expression of Atg16L1, Atg16L2, and GabarapL1 was also observed in H4Swe cell cultures, in the presence of insulin resistance." (PMID 36901549, 2023). "Similar to findings obtained in 3xTg-AD mice, in the presence of insulin resistance, Atg16L1, Atg16L2, and GabarapL1 expression levels were significantly increased." (PMID 36901549, 2023). "Similar to findings in 3xTg-AD mice, we found that Atg16L1, Atg16L2, and GabarapL1 were significantly elevated in insulin resistance conditions." (PMID 36901549, 2023).
kidney carcinoma (1 paper, 2015). Primary or metastatic malignant neoplasm involving the kidney. "Other studies described that a high expression of this gene is associated with a positive outcome in metastatic BC while a low expression of GABARAPL1 was also associated with a poor outcome in kidney carcinoma patients." (PMID 26474850, 2015).
malnutrition (1 paper, 2022). Inadequate nutrition resulting from poor diet, malabsorption, or abnormal nutrient distribution. "In the case of malnutrition, TEX264 connects to Atg8 family proteins through the LIR, preferentially with LC3A, LC3B, and GABARAPL1 in mammalian cells." (PMID 35327508, 2022).
myopia (1 paper, 2016). "Among the mRNAs targeted by differentially expressed miRNAs, there were several (Prkar1a, Rims2, Map2, Gabarapl1, Htr7, Add3, Erc1, Nlgn1) which were involved in synapse formation and function suggesting that synaptic function was one of the biological processes affected in form-deprivation myopia." (PMID 27622715, 2016).
nasopharyngeal tumor (1 paper, 2024). "The underlying mechanism by which GABARAPL1 regulated nasopharyngeal tumor growth was investigated." (PMID 38234672, 2024).
non-small cell lung carcinoma (1 paper, 2021). A group of at least three distinct histological types of lung cancer, including non-small cell squamous cell carcinoma, adenocarcinoma, and large cell carcinoma. "As for ATG genes of other functional units of ubiquitin-like conjugating system, some studies found that GABARAPL1 transcripts were less abundant in breast, prostate, liver and non-small cell lung cancers than matched normal controls, indicating that GABARAPL1 may be a tumor suppressor." (PMID 33604190, 2021).
sarcopenia (1 paper, 2025). Progressive decline in muscle mass due to aging which results in decreased functional capacity of muscles. "KAT2A, CTNNBIP1, GABARAPL1, SEC31A, the expression of IDI1 was highly significantly elevated (p-value < 0.01) in both the Sarcopenia and Control groups in the Sarcopenia dataset GSE8479." (PMID 41325398, 2025).
uveal melanoma (1 paper, 2022). A melanoma derived from melanocytes of the uveal tract. "The risk score for the uveal melanoma TCGA cohort was calculated as follows: risk score = (0.8578 × SQSTM1 expression) + (−1.2004 × ATG9A expression) + (−2.0815 × GABARAPL1 expression)." (PMID 36292980, 2022).